PCNA (proliferating cell nuclear antigen)
Diseases named in the same sentence as PCNA in open-access papers (continued):
Sharing a sentence is not in itself a finding about the gene and the disease.
pancreatic cancer (continued). "In conclusion, proliferative markers including Ki‐67, PCNA, PHH3 and Cyclin D1 have demonstrated promise as predictive and prognostic biomarkers in the context of pancreatic cancer chemotherapy." (PMID 40051490, 2025). "Proliferative markers such as Ki‐67, PCNA, Cyclin D1, and PHH3 hold potential as predictive and prognostic tools in pancreatic cancer management." (PMID 40051490, 2025). "Proliferative markers, such as Ki‐67, PCNA, PHH3, and Cyclin D1, have been investigated for their potential use as predictive and prognostic biomarkers in pancreatic cancer chemotherapy." (PMID 40051490, 2025). "This review explores the potential role of proliferative markers, including Ki‐67, PCNA, Cyclin D1, and PHH3, as predictive and prognostic indicators in pancreatic cancer management, aiming to enhance personalized treatment strategies." (PMID 40051490, 2025). "We conducted a narrative review by searching Scopus, PubMed, and Google Scholar for studies focusing on Ki‐67, PCNA, Cyclin D1, and PHH3 in relation to pancreatic cancer and chemotherapy." (PMID 40051490, 2025). "This narrative review explores the potential of proliferative markers, namely Ki‐67, PCNA, PHH3, and Cyclin D1, as predictive and prognostic tools in pancreatic cancer chemotherapy." (PMID 40051490, 2025). "To re-confirm our IHC/IF results with pancreatic tissues from KPC mice, the saline or GNE-495-treated pancreatic tumor extracts were blotted with antibodies for MAP4K4, MLK3, PCNA, α-SMA, cleaved caspase 3, c-PARP, Bax, and Bcl2." (PMID 34511598, 2021). "Cuc D administration showed a significant reduction (p < 0.05) in the expression of PCNA and MUC13 protein levels in excised xenograft tumor tissues, further indicating that Cuc D has the potential to inhibit xenograft-derived human pancreatic cancer cells." (PMID 31906106, 2019). "Further, the immunoblot analysis also showed that sanguinarine causes a decrease in hypoxia-inducible factor 1 alpha (HIF1α) and proliferating cell nuclear antigen (PCNA) in both BxPC-3 and MIA PaCa-2 pancreatic cancer cells." (PMID 25929337, 2015). "The knockdown of OCT4 inhibited the proliferation and invasion of pancreatic cancer cells (Panc-1) expressing high levels of OCT4, accompanied with decreased expression of AKT, proliferating cell nuclear antigen (PCNA) and matrix metalloproteinase-2 (MMP-2)." (PMID 25017645, 2014). "Recently, it was reported that RRM2, PCNA and MCM2 were downregulated upon treatment with the NSAID NS-398 in pancreatic cancer cells." (PMID 23637916, 2013). "In addition, forced expression of IRF2 increased the expressions of proliferation-related genes cyclin D1 and proliferating cell nuclear antigen (PCNA), suggesting that IRF2 exerted oncogenic activities in human pancreatic cancer." (PMID 30876449, 2019). "The strong positive staining of PCNA in PDAC tissues indicated a higher cell proliferative activity in pancreatic cancer, as compared with negative staining in adjacent normal tissues." (PMID 24116110, 2013). "Finally PCNA, IGFBP6 and Bcl-2 mRNA were upregulated as well as Shh or Gli1 in pancreatic cancer tissues (p < 0.01)." (PMID 19736394, 2009). "Tumor suppressive effects have, for instance, been reported in pancreatic cancer cell lines, where treatment with exogenous biglycan leads to an up-regulation of cyclin-dependent kinase inhibitor p27, down-regulation of Cyclin A and PCNA (proliferating cell nuclear antigen), and cell cycle arrest." (PMID 34917515, 2021). "It was rather unexpected that the downregulation of SOX9 in all the six investigated pancreatic cancer cell lines did not significantly alter the expression of cyclin D1 (CCND1) and PCNA." (PMID 35884771, 2022).
ovarian carcinoma (40 papers, 1995 to 2025). A malignant neoplasm originating from the surface ovarian epithelium. "PCNA and Ki67 are the markers of ovarian cancer, with the former predicting the proliferation of malignant epithelial tumor of the ovary." (PMID 39649540, 2024). "Ovarian cancer cells (PA1) overexpressing SIRT6 were found to show unaltered proliferation depicted by the unchanged expression of the cell proliferation markers PCNA and Ki‐67." (PMID 35686673, 2022). "Our study shows that campesterol decreases the expression of PCNA in ovarian cancer cells, suggesting the potential benefits of using of campesterol as a drug against ovarian cancer." (PMID 33802602, 2021). "In ovarian cancer, strong IGF1R/PCNA colocalization was significantly associated with better disease-specific overall survival (OS) (log rank, p = 0.037)." (PMID 32701997, 2020). "PCNA, a well-known representative ovarian cancer marker, was decreased in the nuclei of fucosterol-treated ES2 and OV90 cells compared to vehicle treatment, respectively." (PMID 32429354, 2020). "When SENP3 was knocked down, the proliferation, metastasis, and invasion of ovarian cancer cells were greatly weakened, and the expression levels of proliferating cell nuclear antigen (PCNA), FOXC2, and neuronal cadherin (N-cadherin) were decreased." (PMID 33192553, 2020). "Ex vivo irradiation of ovarian cancer tissue acutely induced IGF1R/PCNA colocalization together with γH2AX-foci formations." (PMID 32701997, 2020). "Because 4-MU effectively decreased ovarian cancer cell proliferation at a concentration of 1 mM, we further investigated the expression and localization of PCNA, which is involved in DNA replication, in ES2 and OV90 cells treated with 1 mM 4-MU." (PMID 32645961, 2020). "After establishing that most investigated tumor subtypes exhibited IGF1R/PCNA colocalization, we investigated how the interaction was affected by irradiation in ovarian cancer tissue ex vivo." (PMID 32701997, 2020). "In vivo, JS-K inhibited tumor growth, decreased p62 protein expression and increased the expression levels of PCNA in xenograft models which were established using SKOV3 ovarian cancer cells." (PMID 31262254, 2019). "The network based approach identified two 7-gene functional interaction modules (31: DCLRE1A, EXO1, KIAA0101, KIN, PCNA, POLD3, POLD2; 35: DKK3, FABP3, IRF1, AIM2, GBP1, GBP2, IRF2) that are associated with prognosis of ovarian cancer patients." (PMID 27806724, 2016). "Correlation of the cellular proliferation marker index, such as PCNA and Ki-67, with patient survival is also controversial in ovarian cancer." (PMID 16434990, 2006). "Immunohistochemical staining for AT1R, VEGF, CD34 and proliferating cell nuclear antigen (PCNA) were analysed in ovarian cancer tissues (n=67)." (PMID 16434990, 2006). "Next, we assessed the correlation between AT1R expression and tumour proliferation using immunohistochemical staining with PCNA in the same series of ovarian cancer tissues." (PMID 16434990, 2006). "PCNA immunostaining defines a good prognostic subgroup in adequately debulked patients with ovarian cancer." (PMID 7841053, 1995). "Likewise, glioblastoma and head-neckcancers showed similar trends in chromatin modifiers, while breastand ovarian cancers had heightened PCNA levels in the SWI/SNF pathway." (PMID 40657100, 2025). "In vivo, it inhibits ovarian cancer growth, suppressing proliferation markers Ki67 and PCNA." (PMID 38594256, 2024). "The PPCKM inhibited PCNA and Ki67 expressions in the ovarian cancer mice." (PMID 39649540, 2024). "We confirmed that fucosterol inhibits cell proliferation and PCNA expression in ovarian cancer." (PMID 32429354, 2020).
ovarian carcinoma (continued). "To verify whether PTFSs inhibit cell proliferation, we also checked the protein expression of proliferating cell nuclear antigen (PCNA) in both ovarian cancer cell lines by Western blotting." (PMID 32560563, 2020). "Thus, a subset of conventional markers (CA125 and PCNA) can be used to predict overall survival in ovarian cancer patients." (PMID 28978006, 2017). "Moreover, both assays showed that significant higher levels of PCNA protein were observed in samples from patients with stage IV ovarian cancer compared to the ones with stage I or benign diseases." (PMID 28722704, 2017). "However some investigators showed a poor outcome in patients with highly proliferative ovarian cancer tissues while other authors, analyzing a cohort of 92 patients, reported a better five-year survival in tissues with higher PCNA staining." (PMID 24281100, 2010). "However, our immunohistochemical study showed that the AT1R expression score did not significantly correlate with the positivity of the cellular proliferation marker PCNA in ovarian cancer tissues." (PMID 16434990, 2006). "Moreover, IHC staining showed the invasion marker MMP-2, MMP-9, Ki67 and PCNA were down-regulated by the loss of LINC00852, suggesting LINC00852 could promote the invasion of ovarian cancer in vivo." (PMID 34496800, 2021). "Our findings indicate that alpinumisoflavone triggers anti-proliferation in 2D- and 3D-cultured human ovarian cancer (ES2 and OV90) cells, including a reduction in the proliferating cell nuclear antigen expression and sub-G1 phase arrest of the cell cycle." (PMID 35335940, 2022). "In a series of ex vivo irradiated ovarian carcinomas, we found that both low and high dosage of X-ray increased IGF1R/PCNA colocalization together with an increase in γH2AX foci." (PMID 32701997, 2020). "The endogenous level of PCNA protein was measured by both ELISA and SRM assays in 6 different ovarian cancer tissue samples." (PMID 28722704, 2017). "To validate the GSEA results, we then detected the expression of cell cycle (PCNA and PLK1), DNA replication (MCM2 and MCM3) and BER pathways-related proteins (PARP1 and PARP2) in ovarian cancer cells transiently overexpressed ARHGAP10." (PMID 27010858, 2016). "PCNA and CD31 staining were performed to compare proliferation and angiogenesis in TgPTTG ovarian carcinomas compared to age-matched WT animals." (PMID 23164239, 2012). "Furthermore, we also detected the expression of PCNA and MMP9 in ovarian cancer cell lines after transfection with PC-1 siRNA." (PMID 33635867, 2021). "We found that our anti-OSMR monoclonal antibodies reduced the ovarian cancer cell growth and progression by inhibiting STAT3 activation and subsequent oncogenic signaling operated through STAT3, inhibiting the levels of survival regulators such as BCl2, PCNA, and inducing cell death." (PMID 38839865, 2024). "The PCNA expression (28.6 ± 2.4%) in the US + PEG-ZnPP group was significantly lower than that in the US + PpIX and US + ZnPP groups (56.1 ± 2.3% and 47.4 ± 2.1%), indicating that the US + PEG-ZnPP group had significant inhibitory effects on the proliferation of ovarian cancer." (PMID 37765244, 2023).
glioblastoma (32 papers, 2012 to 2026). The most malignant astrocytic tumor (WHO grade IV). "PCNA expression is associated with poor survival and an advanced glioblastoma stage and is recognized as a diagnostic and prognostic biomarker and an effective target for tumor treatment." (PMID 36142368, 2022). "Elevated proteasome and PCNA levels had been previously shown to be associated with increased cell proliferation and in glioblastoma CIC/CSCs." (PMID 23239665, 2013). "In glioblastoma, markers of tumor progression include the expression of proliferating cell nuclear antigen (PCNA), enhancer of zeste homolog 2 (EZH2) and ionic transporters that regulate intracellular chloride levels." (PMID 35216113, 2022). "Here, we demonstrate that ATX-101, a peptide targeting PCNA, has antitumor effects as a single agent and radiosensitizing properties in glioblastoma multiforme models." (PMID 35053455, 2022). "Full-length SHPRH then suppressed glioblastoma progression by inducing proliferating cell nuclear antigen (PCNA) ubiquitination as an E3 ligase." (PMID 33643900, 2020). "To interrogate the conclusion that SMAD2(+) identified the proliferation fraction of glioblastoma cells, we performed double-label immunohistochemistry for pSmad1 or pSmad2 and PCNA in human glioblastoma surgical specimens (n = 4, 15 HPF/specimen)." (PMID 31602000, 2019). "Additional reports demonstrated that cell adhesion molecule VCAM-1-positive glioblastoma tumor stem cells (GTSC) possess a high rate of proliferation as measured by PCNA expression." (PMID 29089868, 2017). "A comparison of tumor subtypes demonstrated that CD133+ glioblastoma cells had a lower incidence of cell apoptosis in the tumor tissue and higher protein expression levels of Oct4, Sox2, PCNA, EGFR, Ang2, MMP2 and MMP9 compared with CD133− cells." (PMID 23251243, 2013). "The CD133+ glioblastoma cell induced-tumor tissue expressed significantly higher levels of Oct4, Sox2, PCNA, EGFR, Ang2, MMP2 and MMP9 proteins compared with the CD133− glioblastoma cell induced-tumor tissue (P<0.05)." (PMID 23251243, 2013). "For example, SHPRH-146aa limits the PCNA protein level and thereby glioblastoma cell proliferation by protecting full-length SHPRH, which is the ubiquitin ligase E3 of PCNA." (PMID 41261216, 2026). "PCNA and EZH2 marker assays of PBT24 and SF8628 glioblastoma tumors transplanted on CAM showed that the PBT24 tumor is less aggressive than the SF8628 tumor." (PMID 35216113, 2022). "The effect on glioblastoma C6, F98, and GL261 cells was measured by accumulation of proliferating cell nuclear antigen (PCNA) and radiolabeled thymidine incorporation." (PMID 34885918, 2021). "Under ALZ003 administration, oncogenic markers, including c-myc, Ki-67 and PCNA, were also obviously decreased in tumor area, indicating that ALZ003 is a potent and safe compound for glioblastoma therapy." (PMID 31896509, 2020). "These primary cells were, also, characterized by high levels of the associated oncogenic signal transduction proteins as pAKT and PCNA compared to NHA and, as expected, oncogenic potential was conserved in U343 glioblastoma cell line." (PMID 31993371, 2019). "The role of miR-149 was explored in glioblastoma where it was found to inhibit the expression of MMP-2, p-AKT1, proliferating cell nuclear antigen (PCNA), cyclin D1, as well as proliferation and invasion in U251 cells." (PMID 24670365, 2014). "Previously, a reduction in PCNA levels after ATX-101 treatment were reported in glioblastoma cell lines; however, this was not the case in JJN3 cells at the ATX-101 doses used in these experiments." (PMID 36564470, 2023). "Moreover, until now, there has been insufficient data regarding the inhibition of proliferating cell nuclear antigen (PCNA) expression by NP-Pt at U118 and U87 glioblastoma cells and tumour tissue." (PMID 28562655, 2017).
glioblastoma (continued). "The mechanism by which CREB regulates glioblastoma tumor cell proliferation involves activities downstream from both the MAPK and PI3K pathways that then modulate the expression of three key cell cycle factors, cyclin B1, cyclin D1 and PCNA." (PMID 27926502, 2017).
osteosarcoma (24 papers, 2005 to 2025). A usually aggressive malignant bone-forming mesenchymal neoplasm, predominantly affecting adolescents and young adults. "We have also found that the expression of USP37 is linked to PCNA in archived osteosarcoma patient samples." (PMID 37118828, 2023). "Compared with low PCNA expression, high PCNA expression was associated with a poor prognosis of osteosarcoma (RR = 1.79, 95% CI 1.14–2.81, P = .011)." (PMID 29019895, 2017). "Some earlier studies showed that high PCNA expression was associated with poor prognosis in the overall survival (OS) of patients with osteosarcoma." (PMID 29019895, 2017). "Several studies have been performed to explore the association between PCNA expression status and prognosis in osteosarcoma." (PMID 29019895, 2017). "Meta-analysis of these 7 studies suggested that PCNA expression was obviously associated with a lower OS rate in patients with osteosarcoma (RR = 1.80, 95% CI 1.45–2.23; P = .000)." (PMID 29019895, 2017). "This meta-analysis demonstrated that osteosarcoma patients with cutoff >10, 25, 50, 75 of PCNA expression were significantly associated with low OS rate." (PMID 29019895, 2017). "Therefore, a meta-analysis including high quality studies was needed to comprehensively evaluate the association of PCNA expression and prognosis of osteosarcoma patients." (PMID 29019895, 2017). "Based on a study of 49 osteosarcoma cases, Lopes suggested that PCNA expression was significantly associated with clinical stage, histological grade, and poor prognosis of osteosarcoma, which could evaluate tumor cell proliferation, and predict its biological behavior and prognosis." (PMID 29019895, 2017). "Various molecular assays, including colony formation, immunofluorescence, immunoprecipitation, and DNA replication restart, were employed to examine the physical interaction between USP37 and PCNA, as well as its physiological effects in osteosarcoma cells." (PMID 37118828, 2023). "The immunofluorescence and western blotting results showed that the RARb antagonist LE135, PPARg antagonist T0070907, LXR agonist T0901317 and Rev-Erba agonist SR9011 reduced the KI-67 and PCNA protein levels in all three osteosarcoma cell lines." (PMID 36681687, 2023). "Patients diagnosed with osteosarcoma displayed elevated levels of PCNA expression, which was positively correlated with heightened URG4 expression." (PMID 37685545, 2023). "Since USP37 was found to interact with PCNA and our molecular docking data further corroborated this finding, the co-expression of PCNA was examined in the osteosarcoma tissue sections." (PMID 37118828, 2023). "To test the clinical relevance of our findings, we analyzed the co-expression of USP37 and PCNA in a retrospective cohort of 40 osteosarcoma patients." (PMID 37118828, 2023). "In our study, we found that PCNA levels increase in response to replication stress in osteosarcoma cells, and we discovered that USP37 interacts with PCNA." (PMID 37118828, 2023). "To further elucidate the cellular processes that are regulated by these NR modulators, we first evaluated the protein levels of two major proliferation markers, namely, KI-67 and PCNA, in osteosarcoma cells treated with the NR modulators for 2 days." (PMID 36681687, 2023). "We studied TFR‐1 and PCNA immunohistochemical expression in fifteen Canine osteoblastic osteosarcomas (COS)." (PMID 32239803, 2020). "Determination of PCNA and Ki67 expression revealed that overexpression of klotho inhibited cell proliferation in tumor tissues obtained from osteosarcoma xenografts." (PMID 32614356, 2020). "Molecularly, IHC analysis of PCNA and Ki67 expression revealed that overexpression of klotho inhibited cell proliferation in tumor tissues obtained from osteosarcoma xenografts, supporting the anti-proliferative role of klotho in osteosarcoma." (PMID 32614356, 2020). "Inhibition of another circRNA CDR1as inhibits the growth of osteosarcoma cells with decreased the expression of PCNA in vivo." (PMID 31772143, 2019).